SAA3P (serum amyloid A3, pseudogene)
Synonyms: formerly SAA3
Gene: Transcribed unitary pseudogene on chromosome 11 (18,112,626 to 18,116,078, reverse strand). Ensembl gene ENSG00000166787.
Diseases named in the same sentence as SAA3P in open-access papers:
SAA3P is named in the same sentence as 2 diseases in open-access papers, as found by Europe PMC text mining. Sharing a sentence is not in itself a finding about the gene and the disease. The quoted sentences say what the papers report.
adenoma (1 paper, 2023). A neoplasm arising from the epithelium. "Six genes (SAA2, SAA1, CRP, SAA3P, PLA2G2A, and APOA4) listed in the heat map also indicated that the expression of PLA2G2A was limited to the adenoma tissue, following the violin plot results." (PMID 38201587, 2023).
colon cancer (1 paper, 2022). "In addition to the downregulation of cytokines, the inflammatory stimulators IL-6 and SAA3P were also downregulated in MTA1-overexpressing CT26 mouse colon cancer cells." (PMID 35350571, 2022).